INS (insulin)
Diseases named in the same sentence as INS in open-access papers (continued):
Sharing a sentence is not in itself a finding about the gene and the disease.
Hypertension (continued). "Recently, Telmisartan, an angiotensin receptor blocker used in the management of hypertension or heart failure, was found to activate the AMPK-Sirt1 pathway in skeletal muscle, and ameliorate insulin sensitivity of obese db/db mice." (PMID 24913149, 2014). "Children with high blood pressure also had significantly higher GGT, LDL-cholesterol, serum fasting insulin, and uric acid values." (PMID 25419656, 2014). "DMac was associated with HbA1c (OR1.48; 95% CI: 1.06–2.06), DM duration (OR 1.16; 95% CI: 1.06–1.26), insulin treatment (OR24.29; 95% CI: 5.02–117.57) and hypertension (OR4.98; 95% CI: 1.06–23.44)." (PMID 24260240, 2013). "The network in the MCA with largest number of down-regulated focus genes affected by hypertension plus hypercholesterolemia showed many molecules related to ERK, Akt, PKC, Vegf, actin, and insulin." (PMID 23874591, 2013). "There is evidence that treatment with rosiglitazone, an insulin sensitizer, improves insulin sensitivity and reduces plasma ADMA concentration in insulin-resistant subjects with hypertension." (PMID 22558392, 2012). "The children who were obese and unfit were significantly more likely to have high blood pressure, cholesterol, CRP and fasting insulin levels." (PMID 22693553, 2012). "In addition to this, patients with PHPT are at increased risk of non-skeletal diseases, such as impaired insulin sensitivity, arterial hypertension and increased risk of death by cardiovascular diseases (CVD), possibly mediated by a chronic low-grade inflammation." (PMID 21698093, 2011). "Insulin and HOMA-OR in children with hypertension was found higher than children with normal blood pressure in our study." (PMID 22187624, 2011). "The CAD patients studied here had a greater prevalence of hypertension and T2DM, higher levels of insulin, TG and apo B, and a greater mean age than the controls." (PMID 21637408, 2010). "Receiving insulin therapy, staying in rural area, no-neuropathy, underweight and normal weight and no-hypertension showed more likely to amputation." (PMID 42302016, 2026). "In addition, the prevalence of hypertension and the use of ACEI/ARB, insulin or fibrate/statin therapy decreased significantly across RC quartiles (all P for trend p < 0.05)." (PMID 41306673, 2025). "The d-ROMs levels significantly differed between the groups with and without hypertension (p = 0.012), thiazolidine use (p = 0.045), insulin use (p = 0.033), female sex (p = 0.021), and by diabetic nephropathy stage (p = 0.013)." (PMID 41381649, 2025). "Module 1 is significantly involved in a series of pathways that may affect the occurrence of hypertension, such as the PPAR signaling pathway, aldosterone-regulated sodium reabsorption, cholesterol metabolism, insulin secretion, and cardiac muscle contraction." (PMID 39854379, 2025). "In contrast, for males the uPDI showed the greatest number of associations with CVD outcomes, but higher scoring participants had higher waist circumference, waist-to-height ratio, insulin, HOMA-IR, and hypertension status, compared to males with lower uPDI scores." (PMID 40426187, 2025). "Similarly, the RBF SVM model utilized ALT, uric acid, body weight, BMI, height, PLT, fasting insulin, total bilirubin, ALB, HbA1c, age, AST, creatinine, TG, LDL-C, DM, sex, TC, HDL-C, and hypertension." (PMID 40361915, 2025). "In contrast, a male patient with musculoskeletal disorders, hyperlipidemia, and neurological disorders, no hypertension, insulin-only therapy, an HbA1c of 7%, FPG of 6–7 mmol/L, BMI of 24 kg/m2, and DBP of 82 mmHg has an estimated PDPN risk of 99%." (PMID 41393290, 2025). "Adjusted for age, gender, a history of hypertension, retinopathy and neuropathy, SD of HbA1C, mean HbA1C, triglyceride, HDL-cholesterol, eGFR, and medications use, including ACEI and/or ARB, aspirin, statin and/or fibrate, and insulin." (PMID 41282290, 2025).
Hypertension (continued). "The results of the univariate linear regression analysis demonstrated that age, alcohol consumption, hypertension, coronary heart disease, T2DM, stroke, glucose, TC, SBP, DBP, BMI, the taking of hypotensive drugs, and the injecting of insulin and Ln CSe were positively related to Ln LAP." (PMID 38612965, 2024). "We then performed mediation analysis involving potential mediators, including anemia, glomerular disease, BMI, hypertension, glycated hemoglobin, HOMA-IR, fasting insulin, low-density lipoprotein cholesterol, triglyceride, intermediate-density lipoprotein and very-low-density lipoprotein." (PMID 38218861, 2024). "This includes those with hypertension, advanced CKD, and those using insulin or metformin." (PMID 39003287, 2024). "Among women, additionally triglycerides, ApoB, insulin, HOMA-IR, ALAT, diastolic blood pressure, hypertension, alcohol intake, and heavy drinking showed a direct association with EAT thickness, while for HDL-C, educational years and annual income inverse associations were observed (Model 1)." (PMID 38796541, 2024). "In the absence of the hypoglycemic effect of insulin, which is characteristic of the IR state, insulin may, in contrast, enhance the hypertensive properties of ANGII and thereby contribute to the hypertension that usually accompanies IR." (PMID 38323106, 2024). "Insulin also induces AT1R overexpression in blood vessels, which may lead to increased biological efficacy of ANGII and thereby induce hypertension and atherosclerosis." (PMID 38323106, 2024). "When adjusted for age, BMI, smoking status, reimbursement for hypertension and diabetes, systolic blood pressure, height, body muscle mass percentage, hs-CRP, 30 min plasma insulin and proinsulin, OGTT 120 min plasma proinsulin, and Matsuda index had nominal associations with incident AS." (PMID 39593205, 2024). "Predictors included younger age, lower adiposity, greater insulin sensitivity, lower diastolic blood pressure, and absence of hypertension." (PMID 38917410, 2024). "A cohort study reported that elevated fasting serum insulin levels and HOMA-IR are linked with hypertension in women, but this association is not seen in men37." (PMID 38880806, 2024). "Our analysis revealed that the benefits of SGLT-2is were most evident in patients without hypertension and without concomitant use of insulin or other OHAs." (PMID 38170522, 2024). "Furthermore, we discovered significant differences (p < 0.05) in race, education level, marital status, family PIR, ALT, ALB, prevalence of hypertension, CVD and Mets, and insulin use among the OBS groups." (PMID 39145317, 2024). "In participants with esophageal cancer higher baseline age, male proportion, BMI, history of DM, hypertension, or CVD, and proportions of lipid-lowering medication and insulin use, as well as low levels of four IR surrogates were observed compared to non-esophageal cancer participants." (PMID 39180548, 2024). "Nevertheless, insulin, beta-blockers (or medications for high blood pressure), and beta-2 agonists (or medications for asthma) were not identified by most respondents as prohibited or potentially prohibited substances." (PMID 39636881, 2024). "Moreover, pharmacological TRPM2 inhibition was shown to improve insulin sensitivity in adipose tissue during angiotensin II-induced hypertension, suggesting that targeting TRPM2 may be a novel therapeutic strategy to treat hypertension-associated insulin resistance." (PMID 38390373, 2023). "And Cheng found abnormal insulin signaling pathways in the brainstem of SHRs during hypertension, which is a potentially important indicator of a lack of brainstem metabolic disorders." (PMID 37304030, 2023). "Therefore, both the pressure overload (hypertension) and humoral factors (RAS activation) as well as insulin resistance that occurred in this rat model were suggested to induce LV morphological hypertrophy and then functional changes." (PMID 37507421, 2023).
Hypertension (continued). "Based on the bioinformatics analysis, we first screened the expression of insulin signaling pathway related proteins in the urine of diabetic patients without hypertension and hyperlipidemia, and then analyzed the function of these proteins." (PMID 36749274, 2023). "In this study, we analyzed the differential expression of insulin signaling pathway related proteins in urine between diabetic patients and NC without hypertension and hyperlipidemia." (PMID 36749274, 2023). "In this exploratory study, we detected the expression of insulin signaling pathway related proteins in the urine of diabetic patients without hypertension and hyperlipidemia." (PMID 36749274, 2023). "Sixteen proteins related to the insulin signaling pathway were screened in urine, and 7 of them were differentially expressed in the urine of diabetic patients without hypertension and hyperlipidemia." (PMID 36749274, 2023). "The objective of this study was to compare the differential expression of insulin signaling pathway related proteins in urine between healthy controls and diabetic patients without hypertension and hyperlipidemia." (PMID 36749274, 2023). "The aim of this study was to analyze and verify the expression of insulin signaling pathway related proteins in the urine of diabetic patients without hypertension and hyperlipidemia, and to explore their clinical application value." (PMID 36749274, 2023). "no hypertension (95% CI 1.82–3.67, p<0.001) and OR 0.73 (95% CI 0.63–0.85, p<0.001) for insulin sensitivity higher by 1 SD." (PMID 33536549, 2022). "The growth factor actions of insulin, acting via insulin-like growth factor (IGF-1), may have an exaggerated hypertrophic response of the left ventricle to arterial hypertension." (PMID 35455055, 2022). "Insulin values were significantly higher in patients with Level 1 MetS than in those considered metabolically normal (i.e., without any of the five IDF criteria defined previously), as was the prevalence of steatosis and hypertension." (PMID 36160146, 2022). "Male proportion, presence of comorbid CKD, hypertension, cerebrovascular disease, and cardiovascular disease, smoking status, and use of insulin and aspirin also showed difference between non-VTDR and VTDR (all P < 0.001)." (PMID 35589921, 2022). "Age, times of insulin use, use of other types of drugs, present HbA1c values, and hypertension were top 5 highest variable importance in No. 27 dataset." (PMID 36466490, 2022). "Moreover, it has been reported that insulin and insulin-like growth factor 1 (IGF-1) are independent predictors of LVH in patients with hypertension." (PMID 35369303, 2022). "The BP nonresponse group had a longer duration of hypertension, more current smoking subjects and diabetic patients, lower eGFR, higher NT-proBNP, increased number of hypertensive agents, and rate of insulin compared with the BP response group (all P < 0.05)." (PMID 36262208, 2022). "In connection to BP, surprisingly, we have found serotonin has been shown to be an important determinant of diastole in obese children without hypertension who had insulin concentrations corresponding to the first to third quartiles." (PMID 35581625, 2022). "Regrettably, the long-term prospective cohort study did not further analyze the relationship between hypertension phenotypes and insulin levels." (PMID 35031663, 2022). "People with higher HVS showed less comorbidity of hypertension and ASCVD but received more insulin." (PMID 36431169, 2022). "The BP nonresponse patients had a longer duration of hypertension, more current smoking subjects and diabetic patients, lower eGFR, increased number of hypertensive agents, and rate of insulin compared with the BP response group (P < 0.05)." (PMID 36262208, 2022). "Every log-10 increment in blood Se was associated with elevated FPG (β = 0.99, 95% CI = 0.34, 1.64) and insulin (β = 21.70, 95% CI = 9.19, 34.21) among participants without hypertension." (PMID 36235626, 2022).
Hypertension (continued). "Early data from 19 patients with essential hypertension but without evidence of diabetes demonstrated that plasma insulin levels were higher in these patients than in the control group." (PMID 36012219, 2022). "With these premises, we sought to investigate the relationships between serum 25(OH)D levels and glucose tolerance and insulin sensitivity in a large group of nondiabetic essential hypertensive patients free of cardiovascular or renal complications." (PMID 35057492, 2022). "On the other side, HDL had a negative correlation with CAVI in hypertension patients and with abdominal aortic stiffness assessed by β stiffness index in subjects with varying insulin sensitivity." (PMID 34330221, 2021). "This implied that the reduced level of antioxidants might involve in the impairments of insulin- and IGF-1-mediated vasorelaxation in hypertension." (PMID 34203897, 2021). "The occurrence of retinal nonperfusion was not related to the ongoing insulin (p = 0.414) or anticoagulant treatment (p = 0.073), the presence of hypertension (p = 0.134) or coronary heart disease (p = 0.789), and the elevated cholesterol levels (p = 0.154)." (PMID 33728349, 2021). "A cohort study showed that higher fasting serum insulin levels and HOMA-IR were associated with incident hypertension in women, but not in men." (PMID 33435964, 2021). "With the exceptions of sex, prevalence of hypertension, and systolic blood pressure, there were significant differences between the insulin and noninsulin groups." (PMID 33502325, 2021). "It was suggested the hypertension observed in these individuals is a result of compensatory mechanisms to the lack of response to insulin at the cellular level." (PMID 33716966, 2021). "This regulation promotes hypertension in obese subjects, which show insulin resistance on peripheral glucose uptake but are not resistant to the effect of insulin on the sympathetic system." (PMID 34827650, 2021). "The majority indicated that younger age, hypertension, poor adherence to the medication, no formal education, and farmer, taking a combination of insulin and oral medication, and smoking were predictors of poor glycemic control." (PMID 33630936, 2021). "The prevalence of hypertension, CKD, and insulin re-sistance were increased with decreasing PA." (PMID 34602927, 2021). "The study aims to explore the relationship between plasma insulin secretion and arterial stiffness in nondiabetic essential hypertensive patients." (PMID 34976408, 2021). "Bidens pilosa’s methylene chloride and aqueous extracts inverted the hypertriglyceridemia and high blood pressure produced by fructose feeding but does not affect plasma levels of glucose and insulin but a fewexperiments showing effect on insulin sensitivity." (PMID 33174095, 2021). "On the other side, insulin activates the mitogen-activated protein kinase (MAPK) pathway, which may promote hypertension, vascular hypertrophy, and CV remodeling." (PMID 32851077, 2020). "At 6–9 weeks postpartum, compared to controls, women in the incident T2D group had higher mean FPG (p<0.001), 2hPG (p<0.001), fasting insulin (p=0.001), 2 hr insulin (p<0.001), fasting TAG (p=0.003), median HOMA-IR (p<0.001) and hypertension (p=0.04), but lower mean fasting HDL-C (p=0.017)." (PMID 32748787, 2020). "Some reports suggest that HFD feeding can induce hypertension in DSSR, as accompanied by body weight increase, visceral fat accumulation, and insulin resistance, while some suggest that HFD only exacerbated the salt-induced elevation in blood pressure and renal injury." (PMID 32748067, 2020). "Selective and reversible inhibition of SGLT2 can lower blood glucose levels independent of insulin status and is also found to manifest favorable effects on hypertension and body weight control, besides maintaining glycemic control." (PMID 31271575, 2019). "For DR, no significance in hypertension or insulin dependency between stages of disease groups was observed." (PMID 31216768, 2019).
Hypertension (continued). "Instead, novel correlations between IGF1R, IRS1, IRS2, and insulin appeared with hypertension demonstrating that IGF1 is no longer responsible for activation of intracellular processes through IGF1R." (PMID 31327319, 2019). "Also, the diminished vasorelaxant effects of insulin and IGF-1 have been found in the development of hypertension." (PMID 30934575, 2019). "Out of the 42 SBP/DBP common pathways, five showed significant enrichment for hypertension GWAS signals (FDR < 0.05), including “Antigen processing and presentation,” “Insulin signaling pathway,” and “Integration of energy metabolism,” and the two positive control sets for SBP and DBP." (PMID 30931314, 2019). "We found that over 6 years follow-up, there were significant trends in association between quartiles of changes in fasting insulin, HOMA-IR and IGR levels and incident hypertension, independent of important baseline confounders and BMI changes." (PMID 31728151, 2019). "The current study conducted among Iranian adults adds to previous studies by showing that changes in serum insulin, HOMA-IR, and IGR levels precede the development of hypertension and might play a role in the pathogenesis of hypertension." (PMID 31728151, 2019). "In a Chinese population of women with PCOS, women with hypertension had higher lipid, glucose, insulin, and HOMA-ir levels than women without hypertension also after adjusting for BMI, which suggested that elevated BP was a marker of metabolic risk." (PMID 29519249, 2018). "We have now shown that the low dose of HK L-137 alleviated LV diastolic dysfunction and reduced serum insulin levels, without affecting hypertension, LV hypertrophy, or cardiac Akt activity." (PMID 29802339, 2018). "Insulin levels further showed positive correlations with hypertension in premenopausal and postmenopausal LNM groups, but not in NLNM groups." (PMID 29533014, 2018). "Compared with participants without T2D, participants with T2D were significantly older, had higher BMI, waist circumferences, fasting glucose, 2-h glucose, fasting insulin, 2-h insulin, HOMA2-IR, and had a higher prevalence of hypertension and coronary heart disease in both cohorts." (PMID 29329254, 2018). "Potential confounders were adjusted stepwise, including gender, age, duration of T2D, duration of DFD, BMI, smoking, hypertension, serum creatinine concentration, levels of white blood cell, HbA1c, DKD, DR, DPN, PAD, metformin, insulin secretagogues, insulin, ACEI/ARB and diuretics." (PMID 28827604, 2017). "There were no statistical differences in body mass, insulin resistance, blood lipids or hypertension between younger and older adults." (PMID 28706732, 2017). "Indeed, additional studies have revealed that the pro-inflammatory PST influences insulin sensitivity and glucose tolerance, whereas CST alleviates adiposity and hypertension." (PMID 28228748, 2017). "Similarly, the pathway-based 2-locus epistasis analysis indicated significant interactions between INSR and PRKCG for SBP and MAP; INS and PIK3R2 for DBP; PIK3CD and ATP1B2 for hypertension in the real data set." (PMID 27980660, 2016). "The most significant interactions for real phenotypes were those between different genes, for example, INS vs. PIK3R2 for DBP, whereas for simulated phenotypes there were significant within-genes interactions such as in INSR gene for SBP, MAP, and hypertension." (PMID 27980660, 2016). "It has, from this perspective, been argued that MetS manifestation is a consequence of high carbohydrate intake, as it attenuates high fasting glucose levels, triggers insulin secretion, contributes to high plasma triglycerides, attenuates the HDL proportion and supports high blood pressure." (PMID 27147943, 2016). "High carbohydrate, high fat-fed rats showed visceral obesity with hypertension, insulin resistance, cardiovascular remodelling, and nonalcoholic fatty liver disease." (PMID 25875119, 2015).